IL22 (interleukin 22)
Diseases named in the same sentence as IL22 in open-access papers (continued):
Sharing a sentence is not in itself a finding about the gene and the disease.
abscesses (7 papers, 2014 to 2025). "The deficiency in Th17 cells and their signature cytokines, IL-17 and IL-22, explains the hallmark susceptibility to mucocutaneous candidiasis and recurrent staphylococcal infections, particularly the characteristic “cold” abscesses." (PMID 41458089, 2025). "It is important to note that, although they exhibited larger lesion (i.e., abscess), the IL-22 KO mice were able to clear these lesions in less than 1 month (data not shown)." (PMID 27375607, 2016). "IL-23 injection induced skin inflammation in the ears, as demonstrated by increased histology scores of multiple parameters (inflammation, abscesses, acanthosis, ulceration, parakeratosis), as well as mRNA expression levels of IL-17A, IL-17F, IL-22 and TNFα, compared with saline treated mice." (PMID 27905482, 2016). "Furthermore IL-22 has previously been shown to down regulate the expression of loricrin, which would reduce the levels available for ClfB to bind to thus further inhibiting abscess formation." (PMID 31009507, 2019). "However, γδ T cells do not appear to induce IL-22 in relation to the IL-17 pathway in mouse models, and mice deficient in αβ T cells have dysfunctional abscess formation in S. aureus wound infection models." (PMID 25309545, 2014). "Corresponding to this, protective efficacy NDV-3 induced increases in CD3+ T-cell and neutrophil infiltration, and IL-17A, IL-22, and host-defense peptide expression in local settings of SSSI abscesses." (PMID 25309545, 2014). "However, the abscess observed in the IL-22 KO mice did not corroborate this idea, as it was larger than the observed in the wild type mice." (PMID 27375607, 2016).
Acute hepatitis (7 papers, 2013 to 2024). Acute hepatic injury resulting from inflammation typically accompanied by increased serum alanine transaminase activity. "Coherently, IL-22 may be a promising therapeutic agent that can reverse the hepatic injury and subsequent coagulation dysfunction in patients with acute hepatitis." (PMID 24799907, 2014). "Interestingly, hepatic MNCs from CCl4-treated RAG-2−/− mice consistently expressed IL-22, although they lack Th17 cells previously known as the source of IL-22 in the development of murine acute hepatitis models." (PMID 23626860, 2013). "However, during the pathogenesis of acute hepatitis models, IL-22 produced by Th17 cells is thought to have a protective role by preventing tissue injury." (PMID 23626860, 2013). "Notch signaling enhanced IL-22 production by CD4+ T cells even in absence of STAT3 by stimulation of AhR in a ConA-mediated acute hepatitis model in RBP-J−/− mice." (PMID 27800305, 2016).
alcoholic liver diseases (7 papers, 2018 to 2023). A disorder caused by damage to the liver parenchyma due to alcohol consumption. "In a murine model of alcoholic liver disease, ethanol-associated dysbiosis reduced AhR activation levels, and thus intestinal Il-22 production was also decreased." (PMID 35742682, 2022). "The ILC3-derived IL-22 production was found to be reduced in an alcoholic liver disease mouse model; IAA supplementation restored the IL-22 level and protected the mice from ethanol-induced steatohepatitis." (PMID 34966278, 2021). "Previous studies demonstrated that in alcoholic liver disease models, the production of IL-22, which regulates the expression of antimicrobial C-type lectin regenerating islet-derived 3 gamma (REG3G), is reduced significantly." (PMID 34683903, 2021). "Due to its hepatoprotective and anti-fibrotic properties, different studies have proposed IL-22 as a plausible candidate in the treatment of alcoholic liver disease (ALD)." (PMID 29892294, 2018). "In addition, Lactobacillus reuteri is engineered to produce mouse IL-22 for treating alcoholic liver disease." (PMID 34683903, 2021). "Moreover, researchers have proposed combining anti-inflammatory drugs with IL-22 as a hepatoprotective IL for alcoholic liver disease (ALD) treatment, and clinical trials of ILs for managing severe alcoholic-derived liver degeneration are ongoing." (PMID 29892294, 2018). "L. reuteri was designed to overexpress the interleukin-22 (IL-22) gene, which increased REG3G abundance in the intestine, reduced inflammation and damage in liver using an alcoholic liver disease mouse model." (PMID 37169742, 2023). "The present study demonstrates that chronic alcohol feeding reduces IL-18 and administration of IL-18 restores intestinal IFN-γ levels (but not IL-22), reverses alcohol-reduced AMP expression, and alleviates alcoholic liver damage." (PMID 33536944, 2020).
anemia (7 papers, 2013 to 2024). A reduction in the number of red blood cells, the amount of hemoglobin, and/or the volume of packed red blood cells. "Observations from a Cameroonian population supported earlier studies in The Gambia, reporting an association of the IL22 + 708T allele with protection against severe anaemia." (PMID 38404582, 2024). "Recent progress has been made in identifying a novel mechanism of IL-22 underlying the development of anemia in CKD patients." (PMID 35432360, 2022). "IL-22 is suggested to have a protective role in severe anemia-associated malaria infection, as it has been reported that IL-22 is elevated in children infected with P. falciparum." (PMID 32148440, 2020). "Our observed associations with disease severity agree with earlier studies in The Gambia that reported an association of the IL22+708T allele with protection against severe anaemia." (PMID 24312262, 2013). "Serum levels of IL-22 are increased in patients with anemia secondary to chronic kidney disease and myelodysplastic syndromes, and the IL-22 receptor, IL-22RA1, is present on erythroid precursors, with blockade of IL-22 signaling alleviating anemia in mice." (PMID 39474425, 2024). "While IL-22 is widely expressed by innate immune cells, the IL-22R was unexpectedly discovered on erythroid precursors, and this receptor was involved in inducing apoptosis in erythroid precursors to exacerbate anemia in CKD patients." (PMID 35432360, 2022). "Moreover, plasma levels of IL-22 are significantly elevated in CKD patients with anemia, and this increase correlates with decreased concentrations of hemoglobin." (PMID 35432360, 2022). "But HIV-infected patients with anemia that is resolved with cART had lower levels of IL-8, IL-18, IL-22, MIP-1-β and MCP-1 and higher IL-6 and hepcidin levels than patients with persistent anemia, either at T0 and T1." (PMID 29258550, 2017). "Second, hyperventilation was not contingent on evident and expected potential triggers such as anaemia (expressed by haemoglobin, haematocrit), infection (expressed by WBC, CRP, IL-6, IL-22), hypoxemia (expressed by pO2 and sO2) or pulmonary congestion on physical examination." (PMID 36207364, 2022).
Behçet’s disease (7 papers, 2013 to 2025). "A study in 18 cases and 21 controls suggested that increased expression of IL-22 was associated with disease activity in Behcet’s disease." (PMID 25297677, 2014). "Elevated levels of IL-17 and IL-22 have been found in the serum and impacted tissues, including skin lesions and mouth ulcers, in Behçet’s disease." (PMID 38674208, 2024). "Th22-type T cell clones from ocular samples taken from Behçet’s disease patients with active uveitis, produced IL-22 and TNF-a but not IFN-γ or IL-17." (PMID 34093536, 2021).
chronic obstructive pulmonary disease (7 papers, 2014 to 2025). A chronic and progressive lung disorder characterized by the loss of elasticity of the bronchial tree and the air sacs, destruction of the air sacs wall, thickening of the bronchial wall, and mucous accumulation in the bronchial tree. "Furthermore, both mouse and human studies of chronic obstructive pulmonary disease (COPD) show that IL-22Ra1 expression by macrophages as well as increased IL-22 expression both are associated with exacerbated chronic obstructive pulmonary disease." (PMID 38101567, 2024). "Elevated Th-22 cells and IL-22 are linked to chronic obstructive pulmonary disease (COPD); however, their mechanisms are not fully elucidated." (PMID 41357311, 2025). "The rs2227485T>C, located in the promoter region of IL‐22, was associated with a decreased risk of chronic obstructive pulmonary disease (COPD) and increased IL‐22 promoter activity, suggesting that this variant might modulate COPD susceptibility." (PMID 35808996, 2022). "A study included 94 patients with COPD, 23 healthy smokers, and 22 healthy control non-smokers found that the increased sputum IL-22 might also play important roles in the pathogenesis of chronic obstructive pulmonary disease (P< 0.01)." (PMID 25297677, 2014).
coronary artery disease (7 papers, 2016 to 2024). "In a study of coronary heart disease, mimic transfection of miR-31 increased the levels of AhR and IL-22 and promoted Th22 cell differentiation." (PMID 36809070, 2023). "To summarize, IL-22 appeared to have an atherogenic effect in a stable coronary disease model in humans, and patients with NSTEMI had higher serum IL-22 levels than those of patients with CCS and healthy controls." (PMID 39274184, 2024). "In coronary artery disease, losartan was shown to decrease IL-6 level, and increase both TGF-β and IL-22 levels." (PMID 35163696, 2022). "In coronary artery disease this medicament decreases IL-6 level, increases TGF-β and IL-22, while in acute myocardial infarction it decreases IL-6, TNF-alfa, and C reactive protein (CRP), which in both cases should lead to alleviation of inflammation-related complications." (PMID 35163696, 2022).
diabetic nephropathy (7 papers, 2017 to 2022). "On one hand, studies in diabetic nephropathy, obstructive nephropathy, and acute kidney injury models indicate that IL-22 plays a vital role in tissue protection and regenerative repair." (PMID 35432360, 2022). "Ameliorating kidney injury of IL‐22 via regulation of metabolism relevant signaling is certificated in cisplatin‐induced kidney damage and diabetic nephropathy animal models." (PMID 33634980, 2021). "In mice, amelioration of kidney injury and necrosis and improvement of kidney functions via regulation of these metabolism relevant signaling and mitochondrial fitness of recombinant IL‐22 are certificated in cisplatin‐induced kidney damage and diabetic nephropathy (DN) animal models." (PMID 33634980, 2021). "Our previous study had demonstrated that IL-22 could alleviate renal lesion and fibrosis in diabetic kidney disease through suppression of NLRP3 inflammasome activation." (PMID 31616439, 2019). "Moreover, our recent study has demonstrated that IL-22 could ameliorate renal lesion and fibrosis in diabetic kidney disease by suppression of renal NLRP3 inflammasome activation." (PMID 31616439, 2019).
E. coli infection (7 papers, 2017 to 2025). "IL-22-expressing ILC3s promote protective immunity against C. rodentium, a mouse pathogen that mimics human pathogenic Escherichia coli infection." (PMID 40539052, 2025). "We can speculate that different cell types secrete IL-17A and IL-22 during an E. coli infection or LPS inflammation episode because IL-17A/F and IL-22 concentration increases in milk did not coincide." (PMID 33059767, 2020). "A recent study published in Nature highlighted the crucial STAT3‐dependent role of IL22 in crypt regeneration and PC maturation, and pointed to the activation in PCs of IL22–STAT3 signaling response after adherent‐invasive E. coli infection." (PMID 36573340, 2023).
hyperandrogenism (7 papers, 2020 to 2025). Excessive secretion of androgens from the adrenal glands or gonads. "These disruptions include glucose metabolic disorders characterized by IR, sexual hormone metabolic disorders dominated by hyperandrogenism, abnormal bile acid metabolic pathways, IL-22 mediated intestinal immune dysfunction, and dysregulation of the brain-gut axis." (PMID 40357203, 2025). "This study showed that insulin sensitivity and ovarian functions in PCOS were modulated by IL-22-associated browning of white adipose tissue, indicating that IL-22 may help treat PCOS with a hyperandrogenism phenotype." (PMID 36835989, 2023). "They hypothesized that IL-22 upregulated the browning of white adipose tissue, resulting in regulated insulin sensitivity and ovarian functions in women affected by PCOS with a hyperandrogenism phenotype." (PMID 33669557, 2021). "Our result shows that the administration of IL-22 evidently improved ovarian function and alleviated hyperandrogenism in this non-metabolic PCOS mouse model, indicating that IL-22 could directly target PCOS ovaries to modulate the process of follicle development and ovulation." (PMID 38734641, 2024).
lymphoma (7 papers, 2013 to 2024). A malignant (clonal) proliferation of B- lymphocytes or T- lymphocytes which involves the lymph nodes, bone marrow and/or extranodal sites. "Interleukin-22 (Il-22) is a 180 amino acid cytokine belonging to the Il-10 cytokine family that was first discovered in mouse BW5147 lymphoma cells treated with Il-9." (PMID 36992680, 2023). "IL-22 was first identified as a product of cytokine-activated lymphoma cells and subsequent studies demonstrated that IL-22 is a major product of the TH17 subpopulation of CD4+ lymphocytes." (PMID 30542269, 2018). "IL-22 is an IL-10 family cytokine that is originally identified from IL-9-stimulated T lymphoma cells and designated as IL-TIF (IL-10-related T cell-derived inducible factor)." (PMID 23577040, 2013). "Agents blocking IL-22, i.e., fezakinumab, could also stop the lymphomagenesis and additionally reduce the ability of the tumorous cells to metastasize in the advanced stages of the lymphoma." (PMID 34948183, 2021).
non-small cell lung carcinoma (7 papers, 2011 to 2022). A group of at least three distinct histological types of lung cancer, including non-small cell squamous cell carcinoma, adenocarcinoma, and large cell carcinoma. "Genetic polymorphisms and plasma levels of IL-22 contribute to the development of non-small cell lung cancer." (PMID 26598081, 2015). "IL-22 is known to induce STAT3 activation, which has also been observed in non-small cell lung cancer and is furthermore associated with poor prognosis, thus being a plausible mechanism for the effects on tumor burden in the mouse model." (PMID 33692792, 2021). "Previous study showed increased serum levels of IL-22 in patients with non-small cell lung carcinoma and IL-22Ra1 expression up-regulated in tumor cells." (PMID 34941188, 2021). "However, sustained IL-22 and epithelial proliferation may promote tumorigenecity, where ILC3s have been identified to be present in high proportions in non-small cell lung cancer (NSCLC) tumor tissues, as well as colorectal cancer." (PMID 29232860, 2017).
osteoarthritis (7 papers, 2013 to 2025). A noninflammatory degenerative joint disease occurring chiefly in older persons, characterized by degeneration of the articular cartilage, hypertrophy of bone at the margins and changes in the synovial membrane. "Increased IL-17 and IL-22 levels are also detected in the synovial fluid of temporomandibular joint of patients with osteoarthritis." (PMID 32189997, 2020). "A study conducted among patients with osteoarthritis showed that IL-1β, IL-6, IL-8, IL-18, IL-17, IL-22, and transforming growth factor-beta 1 (TGFβ1) were increased in the inflamed synovium tissues compared to the noninflamed tissues." (PMID 32189997, 2020). "Serum from patients with RA and osteoarthritis (OA), and healthy controls, and synovial fluid from patients with RA and OA were collected, and the levels of IL-22 and IL-25 were measured." (PMID 32972460, 2020). "We then compared the infiltration of Th1 cells (IFN-γ+ CD4+), Th17 cells (IL-17+ CD4+), and Th22 cells (IFN-γ− IL-17− IL-22+ CD4+) in synovial tissues from patients with osteoarthritis (OA) and those with RA." (PMID 30619268, 2018). "Whereas IL-17 expression was equivalent in PsA, osteoarthritis (OA) and RA ST, IL-22 expression was higher in RA than either OA or PsA ST, in which IL-22 was strikingly absent." (PMID 24286492, 2013).
ovarian dysfunction (7 papers, 2021 to 2025). The inability of the ovaries to function. "In conclusion, IL-22 relies on STAT3 to directly mediate the improvement in ovarian dysfunction in PCOS in a metabolically independent manner." (PMID 38734641, 2024). "The IL-22 levels in serum and follicle fluid of patients with PCOS decreased, whereas the IL-22 administration could improve IR, ovarian dysfunction, dysbiosis of gut microbiota, and prenatal Müllerian hormone in the DHEA-induced PCOS mice." (PMID 35928893, 2022).
skin cancer (7 papers, 2016 to 2022). "Next, we analyzed SOCS3 and SOCS1 levels in SCC and BCC skin tumor lines left untreated or stimulated with IL-22." (PMID 28445952, 2017). "IL-17, in conjunction with IL-22 that are both produced by Th17 cells, supports the development of skin cancer by activating STAT3 in tumor and stromal cells and promoting the infiltration of myeloid cells into the tumor microenvironment." (PMID 31051015, 2016). "Therefore, we investigated the role of IL-22 and IL-22Rα in the induction of skin cancer by analyzing cell cycle changes in keratinocytes exposed to UVB and then treated with IL-22." (PMID 28558005, 2017). "In addition to IL-22, IL-6 and IL-11 also drives the malignant progression of skin cancer cells through the activation of STAT3 and upregulation of inflammatory and angiogenic factors." (PMID 31051015, 2016). "Finally, local or systemic JAK/STAT inhibition by tofacitinib could be crucial for the development of optimized therapeutics also for the treatment of skin tumors characterized by aberrant IL-22 signaling and STAT3 activation in keratinocytes." (PMID 30581877, 2018). "Moreover, the regulation of IL-22 production or IL-22Rα expression might be an effective novel target for skin cancer therapy." (PMID 28558005, 2017). "As a whole, these data provides the rationale for the use in BCC and SCC skin tumors of SOCS3 mimetics, being able to inhibit the deleterious effects of IL-22 in these contexts." (PMID 28445952, 2017). "Furthermore, chronic UV-radiation exposure induces a local immune shift toward RORγt positive IL-17A/IL-22 producing ILC3 that are involved in mutant skin cell growth, thus promoting skin cancer." (PMID 35337918, 2022). "IL-17 and IL-22 produced by Th17 cells enhance skin cancer promotion by activating STAT3 in stromal cells and tumors and by increasing the infiltration of myeloid cells in skin cancer environments." (PMID 33917793, 2021).
squamous cell carcinoma (7 papers, 2012 to 2025). A carcinoma arising from squamous epithelial cells. "Tc22 can exert pro-tumor activity by producing IL-22 in patients with transplantation-associated squamous carcinoma." (PMID 38300330, 2024). "Although IL-22 was frequently observed in both squamous cell carcinomas and basal cell carcinomas, and was confirmed with obvious impacts on them; to our knowledge, this is first report for detailed associations between IL22 and CM." (PMID 32201538, 2020). "All had characteristic interferon-ω autoantibodies, while most also had broader autoreactivity, including IL-22, 17α-hydroxylase, 21-hydroxylase, aromatic L-amino acid decarboxylase (AADC), tryptophan hydroxylase 1 (TPH1), SOX10, NALP5 and squamous cell carcinoma (SCC) antibodies." (PMID 41009535, 2025). "CSA (Cyclosporin) is involved in increasing the Squamous Cell Carcinoma (SCC) by favoring polarization of Th22 which results in increased IL-22 production and thus the blockage of IL22 by using anti-IL-22 antibody could potentially become a viable therapeutic option." (PMID 33042126, 2020).